FOXL1 (forkhead box L1)
Diseases named in the same sentence as FOXL1 in open-access papers (continued):
Sharing a sentence is not in itself a finding about the gene and the disease.
tumor (19 papers, 2012 to 2025). "Consistent with this role as a putative tumor suppressor, loss of FOXL1 has been linked to tumor progression and poor prognosis in several types of cancer, including pancreatic and gastric cancer." (PMID 34298659, 2021). "Among potential targets of miR-188 provided by target predicting tools, FOXL1 attracted our attention because it was implicated in the regulation of epithelial cell proliferation in the gastrointestinal tract and was found in several kinds of tumorous diseases." (PMID 37305399, 2021). "FOXL1 acts as a tumor suppressor and an outcome predictor in pancreatic cancer, clear cell renal cell carcinoma, and osteosarcoma." (PMID 37305399, 2021). "SALL4 expression in adults is restricted to spermatogonia, and is required for long‐term maintenance of SSCs by repressing expression of Foxl1 and Dusp4, two tumour suppressor genes that inhibit SSCs growth and self‐renewal." (PMID 34296486, 2021). "Cell proliferation and invasion assays were performed to determine the effects of EPB41L4A-AS2, miR-301a-5p and FOXL1 on the malignant phenotype of tumor cells." (PMID 30971290, 2019). "FOXL1 overexpression in vivo induced a significant reduction in both tumor volume (P<0.05) and tumor weight (P<0.05)." (PMID 25010679, 2014). "Difference in score of FOXL1-positive immunostaining was also measured between tumor grades (WD vs PD+MD) and was found to be significant (P<0.05), with higher FOXL1 scores in WD groups." (PMID 25010679, 2014). "Also, in vivo experiments proved that EPB41L4A-AS2 suppress tumor growth and extrahepatic metastasis (lung) via the miR-301a-5p-FOXL1 axis." (PMID 30971290, 2019). "Moreover, 2 of tumor samples lack FOXL1 mRNA expression and 3 of tumor samples lack protein expression." (PMID 25010679, 2014). "In summary, our findings suggested for the first time that FOXL1 may play a tumor suppressor role in GBC and downregulation of FOXL1 is a common event in GBC." (PMID 25010679, 2014). "The expression of FOXL1 in subepithelial or intestinal stem cells may contribute to CRC.The current research does not determine whether there are distinct CAF subtypes that play tumor-promoting and -suppressive roles." (PMID 40677714, 2025). "Authors from this review used Foxl1-Cre to determine whether a subtype of HPCs can become tumours." (PMID 35243280, 2022). "Our study is the first research to verify the tumor-promoting role of miR-188 in CRC cells and validate that FOXL1 is the key component between miR-188 and Wnt/β-catenin signaling in CRC." (PMID 37305399, 2021). "A number of TFs were significantly altered in two or more tumour types, including ZEB1, JUN, ELK1, FOXM1, while others were limited to a single type, such as FOXD1 in HNSC and FOXL1 in KIRC." (PMID 28139702, 2017). "Expression of Foxl1 confers on HC11 cells the capability for anchorage independent growth in soft agar and also tumor formation in athymic nude mice." (PMID 23131872, 2012). "Foxl1 expression conferred on HC11 cells the capability for anchorage-independent colony formation in soft agar and tumor development in nude mice." (PMID 23131872, 2012). "SFTPA1, FOXL1, and MAPK11 are tumor-characteristic molecular markers." (PMID 38495669, 2024). "None of the tumours that formed in Foxl1-Cre;RosaYFP mice treated with hepatotoxins were YFP-positive, indicating that tumours were not derived from the Foxl1-expressing HPCs." (PMID 35243280, 2022). "FOXL1 and TGF-β may explain, at least in part, the polarization of CAFs into tumor-promoting GREM1+ CAFs and tumor-retarding ISLR+ CAFs." (PMID 33197448, 2021). "FOXL1 mRNA and protein were examined in tumor tissues and nontumor tissues by RT-PCR, western blot and immunohistochemistry analysis, respectively." (PMID 25010679, 2014).
FOXL1 also shares sentences with these, for which no sentence is quoted: glioma (3 papers); alveolar capillary dysplasia (2); prostate carcinoma (2); renal carcinoma (2); anemia (1); blood disease (1); bone remodelling diseases (1); cardiac diseases (1); cardiac hypertrophy (1); cholestasis (1); cholesteatoma (1); colorectal cancer (1); congenital heart malformation (1); gastric adenocarcinoma (1); Infertility (1); inflammatory bowel disease (1); intestinal atresia (1); kidney cancer (1); liver cancer (1); lymphedema (1); nervous system tumors (1); neurodegenerative disease (1); ovarian granulosa cell tumor (1); Sepsis (1); small intestinal adenoma (1); Tetralogy of Fallot (1); thyroid cancer (1); triple-negative breast carcinoma (1); Umbilical hernia (1); ventricular septal defect (1).